PDCL (phosducin like)
Description:
Acts as a positive regulator of hedgehog signaling and regulates ciliary function. [Isoform 1]: Functions as a co-chaperone for CCT in the assembly of heterotrimeric G protein complexes, facilitates the assembly of both Gbeta-Ggamma and RGS-Gbeta5 heterodimers. [Isoform 2]: Acts as a negative regulator of heterotrimeric G proteins assembly by trapping the preloaded G beta subunits inside the CCT chaperonin.
Synonyms: PHLP; DKFZp564M1863
Tractability: Small molecule: a structure with a bound ligand is known. PROTAC: ubiquitination databases record sites on it; its protein half-life has been measured.
Gene: Protein-coding gene on chromosome 9 (122,798,389 to 122,828,604, reverse strand). Ensembl gene ENSG00000136940.
Subcellular location: Cell projection, cilium
Subcellular location (Human Protein Atlas): Cytosol; Nucleoplasm
Pathways (Reactome):
Metabolism of proteins: Cooperation of PDCL (PhLP1) and TRiC/CCT in G-protein beta folding
Gene Ontology:
Molecular function: protein binding
Biological process: heterotrimeric G-protein complex assembly; positive regulation of smoothened signaling pathway; regulation of G protein-coupled receptor signaling pathway; signal transduction
Cellular component: cytoplasm; cytosol; cilium
Genetic constraint (gnomAD): Loss-of-function variants: 11 observed, 27.95 expected, observed/expected ratio (o/e) 0.39, 90% interval 0.25 to 0.65. The upper end of that interval is the gene's LOEUF score, 0.65, which puts it in group 2 of 6, group 1 being the genes least tolerant of losing a copy. Missense variants: 330 observed, 392.29 expected, observed/expected ratio (o/e) 0.84, 90% interval 0.77 to 0.92. Synonymous variants: 118 observed, 142.72 expected, observed/expected ratio (o/e) 0.83, 90% interval 0.71 to 0.96.
Homologues: Orthologues: chimpanzee PDCL (99% identical), macaque PDCL (98% identical), guinea pig PDCL (95% identical), dog PDCL (93% identical), pig PDCL (92% identical), rat Pdcl (92% identical), mouse Pdcl (92% identical), rabbit PDCL (91% identical), rat AABR07051787.1 (86% identical), tropical clawed frog pdcl (64% identical), zebrafish pdcl (59% identical), Drosophila melanogaster CG7650 (40% identical), and 1 more. Paralogues in human: PDC (38% identical), PDCL3 (22% identical), PDCL2 (19% identical), TXNDC9 (13% identical).
Diseases named in the same sentence as PDCL in open-access papers:
PDCL is named in the same sentence as 8 diseases in open-access papers, as found by Europe PMC text mining. Sharing a sentence is not in itself a finding about the gene and the disease. The quoted sentences say what the papers report.
situs inversus (1 paper, 2022). A congenital condition in which there is complete right-to-left reversal of the position of the major thoracic and abdominal organs (that is, they are arranged in a mirror image of the normal positioning). "In 13 interrupted genes, CACNA1E (in case 12) and STARD7 (in case 17) are known causative and PDCL was found in subject (case 11) with situs inversus for the first time." (PMID 36186435, 2022). "Situs inversus is quite common in patients with ciliary abnormalities in human and PDCL defects found in this study may provide clues for future discovery of the new disease-causing gene." (PMID 36186435, 2022). "Phenotype-association of most of the interrupted genes are unknown, however, PDCL found in case 11 with situs inversus piqued our interest." (PMID 36186435, 2022).
teratozoospermia (1 paper, 2022). "Patients with teratozoospermia exhibit low phosducin-like protein (Pdcl2) expression." (PMID 36253364, 2022).
tumours (2 papers, 2017 to 2022). "First, we confirmed that genetic alterations in our PDCL set matched those observed in tumours: we found multiple copy number alterations (CNA) in all PDCLs, as previously reported for serous OC." (PMID 29180611, 2017). "Together, our data suggest that, in agreement with CA STAT signalling identified using IPA, the GHR pathway may be upregulated in GBMGHR high tumours at several levels: GHR transcription (GHRhigh vs. GHRlow PDCL), GHR protein stabilization and GHR signalling (SOCS2 downregulation)." (PMID 35808822, 2022).
PDCL also shares sentences with these, for which no sentence is quoted: cancer (1 paper); Dystonia (1); glioblastoma (1); movement disorder (1); retinal degeneration (1).